LPA (lipoprotein(a))
Diseases named in the same sentence as LPA in open-access papers (continued):
Sharing a sentence is not in itself a finding about the gene and the disease.
prostate carcinoma (4 papers, 2018 to 2024). A carcinoma that arises from epithelial cells of the prostate gland. "The anti-angiogenic activity of genistein is also investigated in prostate cancer, where it downregulates the genes level of uPAR, MMP-9, VEGF, neuropilin, TSP-1, TSP, TGF-β2, BPGF, PAR-2, protease M, and LPA." (PMID 38611849, 2024).
Cirrhosis (3 papers, 2008 to 2026). A chronic disorder of the liver in which liver tissue becomes scarred and is partially replaced by regenerative nodules and fibrotic tissue resulting in loss of liver function. "RhoA signaling is involved in cirrhosis driven carcinogenesis via LPA pathway as key regulator." (PMID 34469466, 2021).
Crohn disease (3 papers, 2018 to 2025). A gastrointestinal disorder characterized by chronic inflammation involving all layers of the intestinal wall, noncaseating granulomas affecting the intestinal wall and regional lymph nodes, and transmural fibrosis. "For instance, PTVs in CARD9, RNF186 and IL23R provide protection against Crohn’s disease and/or ulcerative colitis and PTVs in ANGPTL4, PCSK9, LPA, and APOC3 protect against coronary heart disease." (PMID 29691392, 2018).
liver disease (3 papers, 2015 to 2024). "Moreover, we have previously shown that LPA variants were able to differentiate between liver disease and patients with HCC." (PMID 25981587, 2015).
abdominal aortic aneurysm (2 papers, 2022 to 2023). Enlargement and ballooning of the vessel that supplies arterial blood to the abdomen, pelvis and legs. "The present study shows that the single nucleotide polymorphisms (SNPs) of the genes CDKN2BAS rs10757278, LPA rs3798220, SORT1 rs599839, DAB2IP rs7025486, and IL6R rs2228145 are associated with the development of abdominal aortic aneurysms (AAA) in a study population." (PMID 37893562, 2023).
coronary artery calcification (2 papers, 2017 to 2024). Calcification of the coronary artery, used as a measure of coronary atherosclerosis, a risk factor for myocardial infarction. "- Specific LPA gene variants increase coronary artery calcification and accelerate necrotic core progression and higher high-risk plaque burden." (PMID 39618878, 2024).
dyslipidaemia (2 papers, 2024 to 2025). "Our study highlighted potential causal links between plasma proteins, dyslipidaemia, and CVDs in South Asians and highlighted protein targets, including CELSR2, PCSK9, ANGPTL3, and Apolipoprotein(a) (LPA)." (PMID 40689090, 2025). "Our study confirmed key proteins (PCSK9, ANGPTL3, LPA), identified potential novel targets (GSTA1, GSTA3, EPPK1, PECR, and PLA2G15), and strengthened evidence for CELSR2 and GAS6 in dyslipidaemia." (PMID 40689090, 2025).
gastric cancer (2 papers, 2022 to 2023). A primary or metastatic malignant neoplasm involving the stomach. "Referring to mining of the GEO database, the GSE26309 dataset was divided into AGS gastric cancer cells Control group, RhoA activator group (LPA), RhoA GEF exchange factor (NET1) knockdown group (shNET1), NET1 knockdown and RhoA activator group (shNET1-LPA)." (PMID 37670284, 2023). "Ubenimex is a broad-spectrum LPA protein inhibitor which can restrain the LAP proteins in many species, such as Leishmania, human liver fluke, plasmodium and E. multilocularis, and inhibit the migration and invasion in gastric cancer by alleviating the activity of the CD13/NAB1/MAPK pathway." (PMID 36311709, 2022).
Hyperglycemia (2 papers, 2022 to 2024). An increased concentration of glucose in the blood. "Several studies have also reported that LPA variants that are considered risk factors for cardiovascular disease and GCKR variants are associated with hyperglycemia." (PMID 35999587, 2022).
lung carcinoma (2 papers, 2019 to 2023). "Additionally, the protein encoded by the LPa gene forms an important part of Lp(a), and Lp(a) is significantly associated with the progression and staging of lung cancer." (PMID 37985446, 2023).
lung fibrosis (2 papers, 2022 to 2023). "The re-activation of developmental pathways is a common theme in organ fibrosis, e.g. wnt and ATX/LPA signaling in pulmonary fibrosis, providing increased plasticity and regeneration potential, as well as increased cell proliferation, migration and invasion." (PMID 37735172, 2023). "Interestingly, several invadosome inducers are upregulated in lung fibrosis, such as TGFβ, PDGF and LPA." (PMID 36613948, 2022).
ovarian tumors (2 papers, 2009 to 2015). "Several ovarian biomarkers, such as Kallikreins, osteopontin, leptin, HE-4, LPA, MUC1 and SLPI, have been identified in the past several years through various approaches, including gene expression profiling and proteomics analysis of ovarian tumors." (PMID 19619303, 2009).
amyotrophic lateral sclerosis (1 paper, 2025). Amyotrophic lateral sclerosis (ALS) is a neurodegenerative disease characterized by progressive muscular paralysis reflecting degeneration of motor neurons in the primary motor cortex, corticospinal tracts, brainstem and spinal cord. "In a genetic model of amyotrophic lateral sclerosis (ALS) in mice, LPA expression was upregulated in the sciatic nerve and skeletal muscle." (PMID 40504302, 2025).
artery stenosis (1 paper, 2019). "A comparison between patients with symptomatic artery stenosis and patients with non-symptomatic artery stenosis showed significant differences between these groups for the rs3798220 polymorphism located in the LPA gene." (PMID 31824394, 2019).
Barrett's oesophagus (1 paper, 2016). "We identified an additional risk locus for Barrett's oesophagus and oesophageal adenocarcinoma (rs12207195) at the gene LPA on chromosome 6q26." (PMID 27527254, 2016).
endometrial cancer (1 paper, 2022). Primary or metastatic malignant neoplasm involving the endometrium (mucous membrane that lines the endometrial cavity). "Quantification analysis in 36 patients with endometrial cancer compared to 36 healthy individuals confirmed the upregulation of APOA1, HBB, CA1, HBD, LPA, SAA4, PF4V1, and APOE." (PMID 36551747, 2022).
HIV-1 infection (1 paper, 2012). The type species of lentivirus and the etiologic agent of acquired immunodeficiency syndrome (AIDS). "The pathogenesis of HIV-1-infection and/or exposure to HAART might contribute to CHD in a stronger way than LPA genetic variants do." (PMID 23230442, 2012).
idiopathic pulmonary fibrosis (1 paper, 2021). Idiopathic pulmonary fibrosis (IPF) is a nonneoplastic pulmonary disease that is characterized by the formation of scar tissue within the lungs in the absence of any known cause. "In the lung, where ATX has been identified as a candidate gene involved in the control of pulmonary functions, increased ATX and/or LPA expression has been reported in asthma and chronic obstructive pulmonary disease, as well as in idiopathic pulmonary fibrosis (IPF)." (PMID 33778909, 2021).
Lyme disease (1 paper, 2010). Lyme disease (named after the towns in the USA where the disease was first identified) is a bacterial infection caused by Borrelia burgdorferi. "Previously, we reported the cloning and expression of full length OspA from B. burgdorferi in a lactobacilli expression vector and designed an oral vaccine candidate for Lyme disease (LpA)." (PMID 20585451, 2010).
sarcoidosis (1 paper, 2016). Sarcoidosis is a multisystemic disorder of unknown cause characterized by the formation of immune granulomas in involved organs. "Several proteins were identified with higher abundance in BAL of sarcoidosis patients, including cadherin 5 (CDH5), transferrin (TF), C-C motif chemokine 24 (CCL24), interleukin 15 (IL15) apolipoprotein A (LPA) and mitochondrial superoxide dismutase (SOD2)." (PMID 27259755, 2016).
cardiovascular disease (58 papers, 2009 to 2026). "Lp(a) is primarily genetically determined through the LPA gene, and variants in the LPA gene are associated with cardiovascular disease." (PMID 36294361, 2022). "Using a comprehensive genetic instrument that separately imputes apo(a) isoform, we show that knowledge of LPA genotypes can better inform incident cardiovascular disease risk prediction than just knowledge of Lp(a) biomarker level." (PMID 29973585, 2018). "LPA SNPs rs3798220 and rs10455872 are consistently associated with Lp(a) levels and result in increased risk for cardiovascular diseases." (PMID 27605514, 2016). "However, the SNPs on chromosome 6 are in close proximity to the LPA gene, which affects plasma concentrations of lipoprotein (a) (Lp(a)) and is strongly associated with cardiovascular disease, a key risk factor for AD." (PMID 41282187, 2025). "However, recent advancements, including the evaluation of antisense therapy targeting the mRNA of apolipoprotein(a) [apo(a)], have sparked immense interest and an evolving body of literature on Lp(a) as a risk factor for cardiovascular diseases." (PMID 39456811, 2024). "However, studies of genetic polymorphisms in the LPA gene indicate that Lp(a) is causally implicated in the development of cardiovascular disease." (PMID 28477314, 2017). "In addition, we discovered a novel cardiovascular protective effect from splice variants in the LPA gene, suggesting that knocking down levels of circulating lipoprotein(a), or Lp(a), can confer a protection from cardiovascular diseases." (PMID 25078778, 2014). "The LPA gene within this cluster expresses the apolipoprotein(a) segment of the Lp(a) lipoprotein particle, which make this cluster involved with cardiovascular diseases by impacting the plasma lipid levels." (PMID 37948393, 2023). "Accordingly, this study did not include individuals with cardiovascular disease, renal impairment, hepatic dysfunction, or identified significant mutations of the LPA gene." (PMID 39647781, 2024). "Lp(a) is recognized as a risk factor for atherosclerotic and non-atherosclerotic cardiovascular disease, with its levels being largely genetically determined and mediated by variations in the LPA gene locus." (PMID 36770634, 2023). "In this direction, the increase in copy number of the LPA gene observed in the ASN population is associated with lower gene-expression levels, which might explain, at least in part, the reduced risk of cardiovascular disease in individuals of this background." (PMID 19789632, 2009). "Cardiovascular disease highlights CDKN2B-AS1, LPA, and SH2B3; respiratory system disease features CHRNA3; psychiatric disorders highlight APOE, APOC1." (PMID 41166152, 2026).
cancer (10 papers, 2011 to 2024). A tumor composed of atypical neoplastic, often pleomorphic cells that invade other tissues. "Nevertheless, there are few reports on a relationship between cancer and LPA polymorphism or expression levels." (PMID 30759150, 2019). "Our approach was confirmed by re-discovery of established cancer targets such as the LPA and mGlu receptor families, but also discovered novel GPCRs which had not been linked to cancer before such as the P2Y Receptor 10 (P2RY10)." (PMID 36513718, 2022). "Their research finally showed that SphK1 is a convergence point of multiple cell surface receptors for three different ligands, LPA, EGF, and S1P, which have all been implicated in regulation of motility and invasiveness of cancer cells." (PMID 21936950, 2011). "Furthermore, correlations between the two PDEIRGs (BIRC5 and LPA) and immune checkpoints of cancer treatment (such as CTLA4, PD-1, and PD-L1) were demonstrated." (PMID 33195412, 2020). "This suggests an important role for the autotaxin/LPA/LPAR1 axis in cancer cell reprogramming." (PMID 31049165, 2019).
tumor (5 papers, 2020 to 2024). "Many studies have pointed out that LPA and its receptors play an important role in the process of tumor cell migration." (PMID 36199069, 2022). "LPA signaling via LPA receptors contributes to the promotion of proliferation, invasion, and metastasis of tumor." (PMID 33408717, 2020). "WB analysis of serum and tumor tissue specimens confirmed the upregulation of eight proteins: APOA1, HBB, CAH1, HBD, LPA, SAA4, PF4V1, and APOE." (PMID 39194522, 2024). "Tumor cells also recruit platelets into the tumor microenvironment (TME), and platelets are activated by tumor cells to release the cytokines VEGF, CCL5, PDGF, TGFβ, PG, TPM3, LPA, PF4, PAF, and HGF, which promote the epithelial-mesenchymal transition of tumor cells." (PMID 35836573, 2022).
neurodegenerative disease (2 papers, 2019 to 2023). A disorder of the central nervous system characterized by gradual and progressive loss of neural tissue and neurologic function. "Along with V180I mutations in PRNP, genetic variations in other genes, such as lipoprotein(a) (LPA), Leucine-rich repeat kinase 2 (LRRK2), and fibroblast growth factor 20 (FGF20), which are directly or indirectly related to neurodegenerative diseases, were also observed in patients with V180I gCJD." (PMID 31238786, 2019).
neurological disease (1 paper, 2021). "These included well-known gene regions such as HLA, LPA, and others, but also Mendelian and neurological disease genes (e.g., GBA)." (PMID 34521442, 2021).
LPA also shares sentences with these, for which no sentence is quoted: peripheral arterial disease (11 papers); coronary atherosclerosis (9); Insulin resistance (9); aortic valve stenosis (8); carotid atherosclerosis (7); kidney disease (7); endothelial dysfunction (6); hyperlipoproteinemia (6); cerebrovascular disease (5); COVID-19 (5); acute myocardial infarction (4); lipid metabolism disorder (4); chronic kidney disease (3); diabetic nephropathy (3); hepatocellular carcinoma (3); Nephropathy (3); Abdominal obesity (2); angina (2); calcification (2); cardioembolic stroke (2); coronary artery stenosis (2); familial hyperlipidemia (2); Hepatic steatosis (2); hyperthyroidism (2); hypertriglyceridemia (2); ischemia (2); metabolic disease (2); metabolic dysfunction-associated steatotic liver disease (2); preeclampsia (2); renal failure (2).
A further 58 diseases each share a sentence with LPA in 2 papers or fewer.